TERT (telomerase reverse transcriptase)
Diseases named in the same sentence as TERT in open-access papers (continued):
Sharing a sentence is not in itself a finding about the gene and the disease.
cutaneous melanoma (continued). "TERT promoter mutations resulting in increased transcription of the TERT gene have been identified as the most common mutation in cutaneous melanoma." (PMID 28380455, 2017). "Two recent reports described activating mutations in TERT promoter in up to 71% of cutaneous melanomas." (PMID 26322273, 2015). "Novel mutations in the promoter region of TERT, coding for the catalytic subunit of the telomerase holoenzyme, were identified in up to 71% of cutaneous melanomas in two recent studies." (PMID 24260374, 2013). "Activating mutations in the TERT promoter were recently identified in up to 71% of cutaneous melanoma." (PMID 24260374, 2013). "From the perspective of the lesion site, the majority of TERT promoter mutations occur at positions -124 and -146, with these mutations being most prevalent in cutaneous melanoma (CM), accounting for 84% of cases, compared to 15% in mucosal melanoma (MM) and 10% in acral melanoma (AM)." (PMID 39871386, 2025). "TERT promoter mutations are less frequent than in cutaneous melanomas." (PMID 39727691, 2024). "TERT promoter mutations are observed at lower frequency than in cutaneous melanomas." (PMID 39727691, 2024). "Further, UV-induced TERT promoter mutations are common in human cutaneous melanoma, and, although they are rare in sun-shielded subtypes, these subtypes have been shown to bear enrichment for other types of mutation that drive TERT overexpression such as SVs and CNVs." (PMID 30188888, 2018). "The lower frequency of TERT promoter mutations observed in mucosal melanomas compared to cutaneous melanomas may be due to the very limited UV-exposure of these tumors." (PMID 29156643, 2017). "TERT promoter mutations in cutaneous melanoma often show UV-signatures." (PMID 24260374, 2013). "Interestingly, like cutaneous melanoma, mutations in the TERT promoter and TERT amplification might upregulate telomerase activity in acral melanoma cells, allowing them to become replicative immortal." (PMID 33256089, 2020). "TERT amplification has been observed in acral melanoma at a higher rate than in other types of cutaneous melanoma." (PMID 40437181, 2025). "The most commonly mutated genes were TERT, BRAF, NRAS, and CDKN2A, consistent with known patterns of mutations in cutaneous melanoma." (PMID 39422848, 2025). "Telomerase reverse transcriptase (TERT) promoter mutations (TPMs) are frequently found in different cancer types, including ∼70% of sun-exposed skin melanomas." (PMID 38371417, 2024). "Promoter mutations enhance TERT expression in human cutaneous melanoma, and these mutations create a de novo binding site for the transcription factor GABP heterotetramer activating TERT transcription." (PMID 35053440, 2022). "After correcting for multiple testing, the only significant promoters were TERT in cutaneous melanoma and pan-cancer; BCL7A, IGLL5, BCL2, and POLR3E pan-cancer; and HNRNPR in uterine adenocarcinoma." (PMID 36396655, 2022). "The frequency of C>T or CC>TT UV-related mutations in TERT promoter region has been found similarly high in basal cell carcinoma (56%), cutaneous SCC (50%), cutaneous melanoma (up to 71%) and conjunctiva neoplasia (43.8%)." (PMID 29562930, 2018). "First identified in 2012 in familial and sporadic cutaneous melanoma,TERT promoter mutations result in ade novo E26 transformation-specific (ETS) factor binding site and increased TERT expression." (PMID 27408703, 2016).
cutaneous melanoma (continued). "Mutations in the TERT promoter that create a novel binding site for T-cell factor (TCF) transcription factors, thereby increasing TERT gene transcription, have been identified in cutaneous melanoma." (PMID 24937153, 2014). "Interestingly, WGS studies analyzed TERT promoter reporting a frequency of 81.2% in acral and cutaneous melanomas." (PMID 32850962, 2020). "As our cohort was mainly composed of non-acral cutaneous melanomas, TERT promoter mutations occurred in 61 (68.5%) samples, which fitted well with previous reports." (PMID 32784823, 2020). "In cutaneous melanomas, an increase of CNVs comes with tumour progression, as TERT amplifications were detected only in invasive melanomas, whereas they were rarely detected in benign naevi, and occasionally present in intermediate lesions, melanomas in situ, and desmoplastic melanomas." (PMID 29751586, 2018). "Besides desmoplastic cutaneous melanomas, TERT amplifications presented the lowest levels in phyllodes tumour of the breast (4%) and oral SCC (2%)." (PMID 29751586, 2018). "We additionally looked for TERT promoter mutations, which have been reported in 71% of human cutaneous melanomas and are associated with UV damage, but no somatic mutations were found within one kilobase of the TERT transcription start site." (PMID 30188888, 2018). "Importantly, TERT promoter mutations are associated with poorer overall survival in patients with non-acral cutaneous melanomas." (PMID 29156643, 2017). "Therefore, it is possible to hypothesize that specific genotypes, including the TERT –245T>C polymorphism, besides the debated SNPS in MC1R (not confirmed by the present study), may influence the occurrence of somatic BRAF mutations in individuals who develop cutaneous melanoma." (PMID 29464027, 2018).
pulmonary fibrosis (54 papers, 2009 to 2025). Chronic progressive interstitial lung disorder characterized by the replacement of the lung tissue by connective tissue, leading to progressive dyspnea, respiratory failure, or right heart failure. "A TERT c.2286 + 1G/A mutation in a splicing consensus site was identified in a patient with pulmonary fibrosis." (PMID 39849589, 2025). "Pathogenic germline variants in telomerase (TERT) cause telomere biology disorders (TBDs) and are associated with bone marrow failure, pulmonary fibrosis, and other complications." (PMID 40456748, 2025). "Family studies have revealed the so-called anticipation phenomenon, characterized by an earlier onset of pulmonary fibrosis symptoms in successive generations of families with TERT mutations." (PMID 40657392, 2025). "The penetrance of pulmonary fibrosis in TERT variant carriers increases with age; it is rare before 40 years but affects about 60% of men and 50% of women over 60 years." (PMID 41465275, 2025). "This has been observed in families with pulmonary fibrosis carrying monoallelic variants of TERC, TERT, or other genes, resulting in early-onset pulmonary fibrosis and other disorders, such as bone marrow failure." (PMID 40095034, 2025). "A subset of patients with pulmonary fibrosis (173/204) were previously evaluated for qualifying variants in telomere-related genes in TERT, RTEL1, or PARN." (PMID 37904125, 2023). "In terms of disease, there are known alterations in TERT that are generally loss‐of‐function mutations and that are found in patients with telomere biology disorders, such as dyskeratosis congenita and pulmonary fibrosis." (PMID 35920280, 2022). "Rare, somatic mutations within the TERT promoter region are also found in non‐malignant diseases, such as in idiopathic pulmonary fibrosis and aplastic anemia." (PMID 35920280, 2022). "The average age of death in ILD smokers with TERT or TERC mutations is 10 years earlier than in mutation-carrying non-smokers, and an association between smoking history and pulmonary fibrosis in TERT mutation carriers ≥40 years of age has been shown." (PMID 33808277, 2021). "Animal models with telomere deficiency in telomerase reverse transcriptase (TERT) have been shown to develop lung fibrosis with higher frequency after repeated low doses of bleomycin." (PMID 34209809, 2021). "A similar study screened 73 probands from the Vanderbilt Familial Pulmonary Fibrosis Registry and found that six (8%) had heterozygous mutations in TERT or TERC." (PMID 34859008, 2021). "A null TERT allele conferred a dominant transmission of disease in a familial form of pulmonary fibrosis (FIP)." (PMID 32218238, 2020). "Mutations in TERT gene, which encodes telomerase reverse transcriptase protein, occur in 1% of DC patients and are associated with mild to severe anemia, liver disease, and often with pulmonary fibrosis." (PMID 32630050, 2020). "In families carrying TERT mutations, pulmonary fibrosis was shown to be the most common disease manifestation." (PMID 31910222, 2020). "Germline mutations of TERT were detected in almost all sample from an adult patients’ cohort suffering from idiopathic pulmonary fibrosis." (PMID 32630050, 2020). "To identify a subgroup of IPF cases with possible telomere related pathology we determined blood and lung telomere length using MMqPCR in 32 sporadic IPF and 17 pulmonary fibrosis subjects with a TERT mutation." (PMID 31910222, 2020). "The authors concluded that there appears to be a significant association between smoking and/or fibrogenic exposures with pulmonary fibrosis in TERT mutation carriers who are ≥40 years of age." (PMID 31426295, 2019). "Other fibrotic conditions such as liver cirrhosis and pulmonary fibrosis have been shown to have a genetic disposition, with mutations seen in the TERT gene responsible for telomere maintenance and repair." (PMID 29293561, 2018).
pulmonary fibrosis (continued). "TERT-specific deficiency in mesenchymal cells caused attenuation of pulmonary fibrosis as manifested by reduced lung hydroxyproline content, type I collagen and α-smooth muscle actin mRNA levels." (PMID 26555817, 2015). "Nevertheless, this degree of TERT/telomerase deficiency was sufficient to cause significant impairment of pulmonary fibrosis, indicative of the essential role of induced TERT in mesenchymal cells for fibrosis." (PMID 26555817, 2015). "In contrast, TERT deficiency reduces myofibroblast differentiation and impairs lung fibrosis, which is partially reversed by transplantation with wild type (WT) bone marrow (BM) resulting in restoration of telomerase induction in BLM-injured lung." (PMID 26555817, 2015). "Taken together, the fibroblast/mesenchymal-specific TERT deficiency resulted in impaired pulmonary fibrosis." (PMID 26555817, 2015). "Mutations in the human TERT gene have been shown to be important in dyskeratosis congenita, aplastic anemia, and idiopathic pulmonary fibrosis, among other disorders." (PMID 24423165, 2014). "In kindreds with familial pulmonary fibrosis and germline TERT mutations, mutation carriers have a reduced life expectancy with a mean age of death of 58 and 67 for males and females, respectively." (PMID 23226558, 2012). "The role of genetic variants in Mucin-5B (MUC5B) and telomerase reverse transcriptase (TERT) in idiopathic pulmonary fibrosis (IPF) pathogenesis, as well as their associations with clinical characteristics, remain uncertain and may exhibit ethnic variations." (PMID 40999395, 2025). "The clinical significance of the remarkable role of the TERT gene was highlighted by a case report of a very rare mutation (TERT 3100C > T) identified in a woman who underwent lung transplantation for familial pulmonary fibrosis and subsequently developed acute graft-versus-host disease." (PMID 39061958, 2024). "Indeed, heterozygous variants have been detected in familial forms of pulmonary fibrosis involving TERT (∼15%), RTEL1 (5–10%), PARN (∼5%), and TERC (∼3%)." (PMID 36833253, 2023). "Moreover, BLM-induced lung fibrosis in WT mice was significantly reduced in myeloid cell TERT-deficient mice as manifested by several markers of fibrosis, including α-SMA (Acta2), type I collagen (col1a2), and TGFβ (Tgfb)." (PMID 36045668, 2022). "Deficiency of TERT affected the proliferation of epithelial cells, and could result in impaired epithelial regeneration and contribute to enhanced pulmonary fibrosis." (PMID 35508454, 2022). "In one case, however, a PNH clone was detected in 4% of neutrophils and maintained stable over 2 years in a patient with a pathogenic TERT variant (D718E) with short telomeres, aplastic anemia, and a family history of idiopathic pulmonary fibrosis (second cousin once removed)." (PMID 35182190, 2022). "In addition, we also demonstrated that telomerase deficiency due to either TERC or telomerase catalytic subunit TERT knockout induces pulmonary fibrosis with AEC2 senescence and senescence-associated low-grade inflammation (SALI)." (PMID 34831112, 2021). "Thus far, TERT variants are the most frequently identified rare variants associated with pulmonary fibrosis; they are found in ~15% of FIP and in 1–3% of sporadic cases." (PMID 28993806, 2017). "Evidence suggests that in autosomal dominant forms of FIP caused by coding mutations in TERT, a unique form of genetic anticipation causes a shift from a pulmonary fibrosis predominant phenotype to one characterized by bone-marrow failure over successive generations." (PMID 26400796, 2015). "Previously, we found that subjects with an inherited predisposition to develop pulmonary fibrosis due to germline TERT mutations have lower red blood cell (RBC) counts, larger RBC size, as measured by the mean red blood cell volume (MCV), and lower platelet counts than family member controls." (PMID 23226558, 2012).
pulmonary fibrosis (continued). "Mutations in the TERT gene have also been described in patients with idiopathic pulmonary fibrosis." (PMID 20700438, 2010). "Additionally, we identified four unrelated families in which loss-of-function TERC or TERT gene mutations tracked with marrow failure, pulmonary fibrosis, and a spectrum of liver disorders." (PMID 19936245, 2009). "Taken together TERT had the potential property of controlling cell proliferation, fate/differentiation, and susceptibility to apoptosis, which might mediate its mesenchymal cell specific role in pulmonary fibrosis." (PMID 26555817, 2015). "Telomere shortening has been deeply studied in IPF, and the presence of pathogenic variants in telomere-related genes, such as TERT, TERC, PARN, and RTEL1 genes, are strongly associated with the risk of developing pulmonary fibrosis." (PMID 40066169, 2025). "A TERT c.2286 + 1G/A mutation in a splicing consensus site was identified in a patient with pulmonary fibrosis, which was estimated as being probably damaging for TERT enzymatic activity, resulting in telomere shortening." (PMID 39849589, 2025). "Rare telomere-maintenance gene pathogenic variants, such as TERT, TERC, RTEL1, and PARN, are principal causes of pulmonary fibrosis and familial pulmonary fibrosis and are associated with shorter telomeres, earlier disease onset, and poor outcomes." (PMID 41465275, 2025). "Four SNPs were associated with pulmonary fibrosis in RA: beyond the well-known MUC5B polymorphism rs35705950 and the TERT polymorphisms rs2736100, TOLLIP (rs111521887) and FAM13A (rs2609255) were also associated with a higher risk of ILD." (PMID 40066169, 2025). "Both pulmonary fibrosis and CHIP are conditions related to aging, and both are also associated with germline variants in TERT." (PMID 37904125, 2023). "Mutations in the genesencoding telomerase reverse transcriptase (TERT) and mucin 5B (MUC5B) are well-known genetic risk factors for pulmonary fibrosis." (PMID 36912407, 2023). "Consistent with the results in human lung tissues, the expression of P16, P21 were increased and KLF4, TERT were decreased in bleomycin-induced pulmonary fibrosis." (PMID 35508454, 2022). "In this study, we aimed to delineate the mechanisms that how TERT protein expression were regulated in alveolar epithelial cells (AECs) in pulmonary fibrosis." (PMID 35508454, 2022). "Double-label immunofluorescent staining method showed that TERT was decreased in AECs in bleomycin-induced pulmonary fibrosis." (PMID 35508454, 2022). "We found that in bleomycin-induced lung fibrosis models, pulmonary fibrosis were more severe while TERT expression was downregulated." (PMID 35508454, 2022). "Genetic mutagenesis of TRF2 or telomerase genes induces pulmonary fibrosis, whereas transgenically expressing TERT holds a therapeutic potential in alleviating pulmonary fibrosis." (PMID 35269498, 2022). "qPCR and western blotting were performed and confirmed that expression of TERT was down-regulated and P16, P21 together with fibrotic markers (αSMA and Collagen-I) were increased in bleomycin-induced pulmonary fibrosis tissues at both mRNA and protein levels." (PMID 35508454, 2022). "TERT expression in epithelial cells was reported to be able to resist bleomycin-induced pulmonary fibrosis." (PMID 35508454, 2022). "In conclusion, the present study demonstrates that the transcription factor KLF4 attenuates bleomycin-induced lung fibrosis by protecting TERT expression and telomere length." (PMID 35508454, 2022).